XBP1 (X-box binding protein 1)
Diseases named in the same sentence as XBP1 in open-access papers (continued):
Sharing a sentence is not in itself a finding about the gene and the disease.
infection (continued). "Using three independent approaches to study the role of XBP-1 in the course of MCMV infection in fibroblasts, it was clear that removal of XBP-1 either before infection or early after it, delays the expression of viral proteins." (PMID 25333725, 2014). "Infection of Huh7 with JFH1 provoked an acute ER stress response concomitant with ATF6 cleavage, XBP1 splicing and PERK phosphorylation at 6–9 dpi followed by a chronic and milder ER stress with a diminished CHOP level at 15–22 dpi." (PMID 24904547, 2014). "Total RNA was isolated at 72 h post-infection, and the message levels of GRP78, XBP1, GADD34 and CHOP were examined by real-time RT-PCR." (PMID 25409163, 2014). "For instance, one report on DENV describes early PERK activation followed by inhibition, XBP1 induction mid-infection and ATF6 activation late in infection." (PMID 24904537, 2014). "Quantitative real time PCR analysis showed that the transcription levels of both XBP-1 gene (~9 fold) and EDEM-1 (~16 fold) increased at 48 h post infection." (PMID 23356742, 2013). "Early after infection (12 h), DENV did induce the IRE1-XBP1 pathway of the UPR, but expression of XBP1 was localized to the ER and not the nucleus." (PMID 22675522, 2012). "At 33 hr post-infection, several major components of the UPR pathway were up-regulated, including BiP, PERK, ATF6, IRE1, GADD34, CHOP and XBP-1." (PMID 23170826, 2012). "The silencing of XBP1 reduces infection by suppressing IFN-1β expression, while also decreasing heme oxygenase (HO) levels and increasing nitric oxide (NO) concentrations, further highlighting XBP1’s critical role in parasite proliferation within macrophages." (PMID 40149586, 2025). "However, cells infected with the EMCV variant deficient in 2A protein continued to exhibit the suppression of XBP1 mRNA splicing, similar to wild-type EMCV infection." (PMID 40143290, 2025). "Upon infecting fibroblasts with the HSP47 lentivirus, a PCR product derived from spliced XBP1 (XBP1-s) mRNA, spliced from unspliced XBP1 (XBP1-u) mRNA, was detected, while infection of the vector virus did not yield a PCR product derived of XBP1-s mRNA." (PMID 38534372, 2024). "Another study found the induction of XBP1 processing by the non-structural protein NS2B in infection with DENV-2." (PMID 39459886, 2024). "Despite the evident activation of IRE1 during the lytic cycle of KSHV, we observed a minimal XBP1 mRNA splicing (XBP1s) and XBP1s protein, a direct product of IRE1 activity, indicating disruption of canonical IRE1 signaling during lytic infection in iSLK.219 cells." (PMID 39471213, 2024). "However, this study suggests an additional mechanism, in that both XBP1 and PERK contribute to stress-mediated dsDNA release in response to infection with the RNA VSV virus." (PMID 39100663, 2024). "In addition, they detected the translocation of XBP1 and ATF6 to the nucleus of infected cells in the brain of mice five days after infection, indicating activation of these pathways." (PMID 39459886, 2024). "Although we did not observe specific XBP1 or BiP cleavage products during EV-D68 infection, a recent study showed that PV and CVB3 induce cleavage of XBP1 at late time points during their infection." (PMID 37850626, 2023). "Since EV-D68 infection inhibits ER stress, as indicated by the decrease in XBP1 and BiP protein levels, and the lack of BiP induction when EV-D68-infected cells were treated with TG, this suggests that ER stress is detrimental to EV-D68 release." (PMID 37850626, 2023). "Conversely, the expression abundance of ATF6, cleaved ATF6, and p-IRE1 did not display fluctuation during infection, and the spliced form (XBP1s) of XBP1 was not detectable at the mRNA level." (PMID 36939351, 2023). "Since XBP1 is not responsive to infection, we sought to determine if TRAF2 has a functional role during pathogen colonization." (PMID 35862781, 2022).
infection (continued). "This was consistent with significant upregulation of DNAJB9 and total XBP1 during infection with MERS-CoV but not SARS-CoV-2." (PMID 36125275, 2022). "MERS-CoV but not SARS-CoV-2 induces XBP1 splicing during infection of biologically relevant iPSC-derived alveolar type II cells." (PMID 36125275, 2022). "In addition, we obtained flies with fat body-specific RNAi of Sip3 combined with Xbp1, PERK, or Atf6 RNAi and conducted infection experiments." (PMID 36741393, 2022). "The infection of all three cell lines with the three TBFV was performed as before, but cell lysates were harvested at different time points for the extraction of mRNA, RT-PCR and subsequent detection of spliced and unspliced forms of XBP1 cDNA." (PMID 34834970, 2021). "Similarly, infection with B. melitensis activated ISR-independent branches of the UPR as shown by upregulated expression of BiP, CHOP, and increased splicing of XBP1." (PMID 33996904, 2021). "Neither infection with SARS-CoV nor overexpression of SARS-CoV S protein induces XBP1 mRNA splicing." (PMID 35003039, 2021). "Similarly, the IRE1 activation marker XBP1 was expressed at high levels in SNB19 cells at 24 and 48 h post infection with TBEV Neudoerfl, but was only mildly induced in cells infected with the other two TBFV." (PMID 34834970, 2021). "Similar to XBP-1 and UPRER, OST-regulated N-glycosylation is crucial for ER protein homeostasis, and we showed that the OST contributes to protection against PA14 infection." (PMID 32130226, 2020). "Together, these data support the hypothesis that IRE1α and XBP1 contribute to ZIKV replication not only in cultured cells, but also in an adult animal model of infection." (PMID 32138181, 2020). "Even with an extension of the infection time to 15 h, spliced XBP1 transcripts were still not detected." (PMID 30717233, 2019). "Infection induced robust XBP-1 splicing that was inhibited by 4μ8c but not by GSK PERK inhibitor D3 demonstrating that C. trachomatis infection was causing activation of IRE1α RNAse activity." (PMID 27021640, 2016). "Deletion of XBP-1 from PMs upon infection with the CRE expressing virus did not alter the expression of neither viral mRNA nor protein." (PMID 25333725, 2014). "In one we ubiquitously removed XBP-1 before infection and in the second we used Cre-expressing viruses to remove XBP-1 only in infected cells, an approach that was previously used to demonstrate the role of Blimp1 for MHV-68 infection and to monitor viral dissemination in vivo." (PMID 25333725, 2014). "On the other hand, although SARS-CoV belongs to the same genera of Betacoronavirus as MHV, neither infection with SARS-CoV nor overexpression of SARS-CoV S protein induces XBP1 mRNA splicing." (PMID 24987391, 2014). "It is unlikely that viral glycoprotein expression is responsible for this very early induction of Xbp1 mRNA splicing as viral glycoproteins are not expressed in large quantities so early after infection." (PMID 23950715, 2013). "What are the functional consequences of the elevated ER stress present in the xbp-1 mutant under standard growth conditions, in the absence of infection?" (PMID 22125500, 2011). "Infection of shRIG-I and HUH-7 cells by DV1 resulted in splicing of XBP1." (PMID 21245912, 2011). "In contrast to the previous experiment, we found no inhibition of Xbp1 mRNA splicing in the DTT-treated infected cells throughout the entire course of infection, as the relative level of the Xbp1s mRNA isoform was roughly similar to that observed in the DTT-treated mock-infected cells." (PMID 36366584, 2022). "Finally, in another more distant member of the Reoviridae family, the pathogenic rotavirus, the cytoplasmic splicing of the stress‐related factor XBP1 is altered following infection with some but not all of the rotaviral strains." (PMID 31034770, 2019). "Moreover, the unspliced form of Xbp1 did not appear significantly affected neither by infection nor by tunicamycin treatment." (PMID 27978534, 2016).
infection (continued). "Infection of the hepatocyte sub-line Huh7.5.1 with JFH1 (2a) induced an acute ER stress peaking at 2–5 days post-infection (dpi), concomitant with phosphorylation of IRE1, eIF2α, and JNK, XBP1 splicing, ATF6 cleavage and upregulation of GADD34, ERdj4, P58IPK, ATF3, ATF4, and CHOP." (PMID 24904547, 2014). "For instance, it has been documented that infection by the Hepacivirus hepatitis C virus (HCV) leads to the activation of the three UPR signaling pathways including BiP expression, IRE1 activation, and Xbp-1 splicing, ATF6 cleavage, eIF2α phosphorylation, and induction of CHOP expression." (PMID 24917859, 2014). "This led us to assume that apart from its antiviral activity, XBP-1 might possess a pro-viral role that allows the promotion of viral genes transcription, conferring a lower infection rate in the absence of XBP-1 despite lower levels of IFNβ." (PMID 25333725, 2014). "However in the case of SINV infection, the spliced XBP-1 gene transcript was much more prominent than was observed for CHIKV, starting from 12 h post infection with dramatic increase in the spliced product at 24 and 48 h post infection." (PMID 23356742, 2013). "However, at 8 hours post-infection there was a faint and reproducible XBP-1 signal in MNV-1 infected cells, albeit not significantly different from DMSO controls." (PMID 22792064, 2012). "Given the interaction of XBP1 and sigma-1 receptor in the ER, it is likely that sigma-1 receptor agonists (i.e., fluvoxamine), which may block EBV reactivation, would be potential therapeutic drugs to limit clinical deterioration after infection and long COVID symptoms." (PMID 37402856, 2023). "The findings indicated that spliced XBP1 mRNA was absent in PK-15 cells infected with PTV-GXLZ2024, suggesting that the IRE1α-XBP1 pathway was not activated following infection with PTV-GXLZ2024." (PMID 41012628, 2025). "We observed the non-canonical splicing of the XBP1 mRNA (XBP1s) in ZIKV-infected microglia at 24 and 48 hpi indicating the activation of the IRE1 endonuclease activity upon infection." (PMID 41157563, 2025). "The levels of unspliced XBP1 RNA were increased >5-fold in hTERT-RPE1 after thapsigargin treatment, irrespective of HAdV5 infection, but were little changed in A549." (PMID 40005508, 2025). "In contrast, UPR markers XBP1s, p-eIF2α, GRP78, XBP1, and CHOP did not increase in response to infection but paralleled the kinetics of AST and De Ritis ratios." (PMID 35372445, 2022). "Both pathways were not activated in neuronal SH-SY5Y cells upon infection with TBEV Neudoerfl or LGTV, but were induced at 24 h in TBEV HB171 infected cells with ATF6 and p-eIF2α levels detectable even earlier than XBP1 in these cells." (PMID 34834970, 2021). "On the other hand, infection in neuroblastoma cells leads to high levels of ATF6 activation, with transient eIF2α phosphorylation, while XBP1 splicing seems to have no role in viral replication." (PMID 32106582, 2020). "WP1130 treatment induced XBP-1 activation as early as 1 hour after infection with MNV-1 or mock lysate and reached statistical significance at 8 hours post-infection, although not as robustly as the positive control thapsigargin." (PMID 22792064, 2012). "In addition, transcription of the Xbp1 gene is significantly induced during VACV-WR infection in relation to mock-treated cells, but not during MVA infection or in tunicamycin treated cells." (PMID 37434252, 2023). "Importantly, stt-3 RNAi did not decrease the shortened survival of xbp-1(-); pmk-1(-) mutants upon PA14 infection." (PMID 32130226, 2020). "Therefore, it appeared that HRV16 infection did not induce the expression of the active XBP1 transcript, indicating that IRE1 was not activated upon HRV16 infection." (PMID 30717233, 2019).
infection (continued). "By examining the three branches of UPR marker molecules PERK/eIF2α, ATF6, IRE1α/XBP1 splicing, we find that UPR did not occur until 24 h post-infection (hpi) as shown by elevation of phosphorylated form of PERK and eIF2α (p-PERK and p-eIF2α), a similar time point when autophagy was induced." (PMID 26907328, 2016). "For example, infection with WNV NY-99 strain activates all three pathways of the UPR, while infection with the WNVKUN strain activates the ATF6 and XBP-1 pathways but not the PERK pathway, and this may be due to differences in the viral strains and/or cell lines used." (PMID 30842332, 2019). "And the expression of ZIKV-ENV do not correlate with the XBP1 expression or its translocation into the nucleus, this suggested that ZIKV-ENV may not be responsible for induction of IRE1-XBP1 pathway or IRE1-XBP1 pathway activated in the infection state with the low expression level of ZIKV-ENV." (PMID 30241539, 2018).
metabolic disease (15 papers, 2013 to 2026). A congenital disorder (due to inherited enzyme abnormality) or acquired (due to failure of a metabolically important organ) disorder resulting from an abnormal metabolic process. "The recent discovery of 12-h rhythmicity in both global gene expression and rhythmic activation of the ER stress transcriptional factor XBP1 in the mouse liver offers unique opportunities to define the role of 12-h clock oscillators that underlie normal physiology and metabolic disease." (PMID 33277471, 2020). "Recent studies have shown that compounds targeting the XBP1 pathway are a potential approach for the treatment of metabolic diseases." (PMID 34503513, 2021). "The two studies above and our own work suggested a protective role of IRE1α/XBP1 pathway which distinguishes from PERK/CHOP pathway in metabolic disorders." (PMID 24223162, 2013).
neurodegenerative disease (13 papers, 2012 to 2025). A disorder of the central nervous system characterized by gradual and progressive loss of neural tissue and neurologic function. "Thus, we report here that XBP1 and the ER stress play different roles in neurodegenerative diseases, although the mechanisms underlying these differences are not clear." (PMID 22528838, 2012). "XBP1-s is also closely related to the induction of neurodegenerative disease through its regulation of motor and memory function." (PMID 35269888, 2022). "This dual effect of the UPR in conformational diseases was already reported for neurodegenerative diseases, where the role of spliced Xbp1 seems to differ depending on the context." (PMID 28437467, 2017). "Other more unexpected targets connect spliced XBP-1 to DNA damage and repair pathways, myodegenerative and neurodegenerative diseases." (PMID 25216759, 2014). "Thus, while further investigations are still needed, this finding indicates the possible role of XBP1-u on neurodegenerative diseases." (PMID 35269888, 2022). "Therefore, XBP1 may act as a molecular target for modulating neuronal cell survival in neurodegenerative diseases." (PMID 36768338, 2023). "Therefore, impaired Xbp1 activation might affect axonal ensheathment and concomitantly certain protective roles of glial cells leading to the brain degeneration observed in these flies." (PMID 29563863, 2018). "Recent studies have demonstrated an involvement of the IRE1α-XBP1 and ATF6 pathways in human neurodegenerative diseases." (PMID 29725981, 2018). "The activation of the IRE1α-XBP1 and ATF6 pathways is triggered in ALS as well as other neurodegenerative diseases." (PMID 29725981, 2018).
kidney diseases (7 papers, 2022 to 2025). "Collectively, these findings support the notion that loss of XBP1 potentially contributes to the progression of renal diseases." (PMID 35765067, 2022). "Among them were several genes known to be involved in kidney diseases, such as Kdm5a, Rb1, Tead1, Xbp1 and Ppargc1α with so far unknown role as sexual dimorphism regulators." (PMID 39278930, 2024). "XBP1, a key component of endoplasmic reticulum stress, plays a pivotal role in kidney diseases." (PMID 39061070, 2024).
adenocarcinoma (5 papers, 2010 to 2025). A common cancer characterized by the presence of malignant glandular cells. "A group of 14 Xbp1/Rnaseh2bΔIEC mice and 10 Atg16l1/Xbp1/Rnaseh2bΔIEC mice were histopathologically analyzed, which confirmed that both genotypes largely developed adenocarcinomas." (PMID 41057521, 2025). "Inhibition of either IRE1α/XBP1 or PERK pathways blocks UPR-mediated generation of procoagulant EVs from adenocarcinoma cells." (PMID 37651191, 2023).
bacterial infection (4 papers, 2013 to 2023). "XBP-1 deficiency in mice increases their susceptibility to both bacterial infections and impairs their host defense." (PMID 35497095, 2022). "In addition, previous studies indicate that deficient XBP-1 increases mice's susceptibility to bacterial infections and impaired host defenses." (PMID 35497095, 2022). "Further, we subjected flies with fat body specific down regulation or ectopic expression of Xbp1 to bacterial infection." (PMID 36741393, 2022). "The expression of LAP, XBP1, and TAP was significantly increased; among them, TAP and LAP, as defensins, can provide innate defense against bacterial infection in dairy cows." (PMID 37684984, 2023). "Although previous data reported XBP1 mRNA splicing by intracellular bacteria such as Francisella, this is one of the first reports of more widespread UPR induction resulting directly from intracellular bacterial infection rather than toxin production." (PMID 24339776, 2013).
inflammation (4 papers, 2017 to 2023). Aberrant reaction of the microcirculation characterized by movement of fluid and leukocytes from the blood into extravascular tissues. "Loss of XBP1 induces Müller glia activation and promotes retinal inflammation in DR." (PMID 31242599, 2019).
cardiovascular diseases (3 papers, 2022 to 2024). "In cardiovascular disease, cardiomyocyte-specific deletion of XBP1 aggravated cardiac dysfunction in ischemia-reperfusion injury, suggesting that XBP1s has a protective effect." (PMID 35321102, 2022).
psychiatric disorder (3 papers, 2022 to 2024). A disorder characterized by behavioral and/or psychological abnormalities, often accompanied by physical symptoms. "Hence, these results raise the interesting hypothesis that dysfunctions of the Xbp1 axis could also regulate both neurodevelopmental and psychiatric disorders." (PMID 35831437, 2022).
skeletal disease (3 papers, 2015 to 2022). "IRE1α and its downstream target, XBP1, are activated in the skeletal muscle of mice upon injury, and this branch is essential for alleviating protein aggregation related to skeletal disease." (PMID 36456548, 2022).
cardiac diseases (2 papers, 2014 to 2015). "Hence, upregulated of miR-214 under prolonged cardiac stress maybe contribute to XBP1 downexpression in maladaptive cardiac diseases." (PMID 26572862, 2015). "Both, the increase of spliced XBP1 and activation of ASK1 potentially contribute to the pathogenesis of heart diseases." (PMID 24892553, 2014).
hematologic malignancies (2 papers, 2022). "In conclusion, in this study we show that c-Myc can be considered a molecule at the cross-road between UPR and DDR in correlation with its capacity to cross-talk with the IRE1α/XBP1 arm of UPR, as observed in these hematological malignancies." (PMID 35453482, 2022). "Recently published data demonstrate the significance of the IRE1α-XBP1 axis of the UPR network in solid tumors and hematologic malignancies." (PMID 35790913, 2022).
hematological cancers (2 papers, 2021 to 2022). "However, the importance of targeting the IRE1alpha/XBP1 axis in vivo and in vitro has been reported by a variety of studies, particularly those focused on hematological cancers." (PMID 33513694, 2021).
benign tumors (1 paper, 2025). "In clinical specimens, XBP1 expression in ovarian tissues from patients with OvCa was remarkably higher than that in ovarian tissues from patients with benign tumors." (PMID 40105652, 2025).